INS (insulin)
Diseases named in the same sentence as INS in open-access papers (continued):
Sharing a sentence is not in itself a finding about the gene and the disease.
Insulin resistance (continued). "TCC can increase the HDL-C and quantitative insulin sensitivity check index (QUICKI), but decrease the serum levels of insulin, homeostasis model assessment-estimated insulin resistance (HOMA-IR), log(HOMA) and ET-1." (PMID 32784834, 2020). "A lower HOMA-IR value is expected to reflect higher insulin sensitivity; higher HOMA-IR values lower insulin sensitivity or insulin resistance." (PMID 32796637, 2020). "Also consistent with the current results in obese CHF, early paradoxical increments in insulin signaling protein activation have been notably reported in experimental high-fat diet-induced obesity models, even in the presence of elevated circulating blood glucose and systemic insulin resistance." (PMID 33158222, 2020). "Because the main feature of the pathogenesis of DM that is linked to NAFLD is insulin resistance, the impact of a decrease in insulin secretion on incident DM may not be substantial, and therefore may be missed in the studies with small sample size and/or of short duration." (PMID 32978491, 2020). "Taking into account the notable role of insulin resistance in PCOS pathogenesis, the application of insulin sensitizer medicines, such as inositols, can be effective in the amelioration of PCOS symptoms." (PMID 32992734, 2020). "In agreement with this, a recent report concluded that an inhibition of the FOXO1/Pgc-1α pathway regulated hepatic gluconeogenesis and improved insulin resistance in rats fed with a HFD and insulin-resistant cells." (PMID 33348802, 2020). "We assessed the effect of PvrAct expression in hemocytes on peripheral insulin and inflammatory signaling in HSD condition and observed restoration of certain features of insulin resistance." (PMID 32849518, 2020). "Subjects with insulin resistance and T2DM are characterized by impaired insulin action and body glucose uptake in the skeletal muscle." (PMID 32326182, 2020). "As our METS FMT donors were characterised by lower peripheral insulin sensitivity (Rd) than their METS recipients, a gut microbiota-driven transmissible trait of insulin resistance in obesity is a tempting explanation." (PMID 31147381, 2020). "It has been reported that supplementation of carnitine can decrease body weight gain, adiposity, insulin serum concentration, and TAG liver content and improve insulin resistance in obese Zucker rats." (PMID 32733621, 2020). "Mice fed the VHF or HFHS diets displayed elevated fasting plasma glucose and insulin levels compared to LF-fed mice, leading to higher HOMA index of insulin resistance (HOMA-IR) index suggestive of insulin resistance after VHF or HFHS feeding." (PMID 32977558, 2020). "In conditions of insulin resistance such as central obesity, T2DM with obesity and hypertension, the inhibitory effects of insulin on platelets are impaired." (PMID 31963572, 2020). "Resistin influences insulin homeostasis, but the relationship between its serum levels and DM2, insulin resistance, or obesity is unclear and an increase in resistin levels correlated with these pathologies is still questionable." (PMID 33182462, 2020). "Muscle-specific knockout of GLUT4 in mice led to systemic insulin resistance and a mild diabetic phenotype whereas overexpression of GLUT4 improved glucose tolerance and insulin sensitivity in normal as well as genetically diabetic db/db mice." (PMID 32591906, 2020). "In this model, overt hyperglycemia results from a combination of insulin resistance induced by HFD feeding and defects in insulin secretion induced by single low-dose (40 mg/kg) STZ treatment." (PMID 32831998, 2020). "We regressed DNA methylation age acceleration from the three models in blood and sperm onto five weight-related or metabolic traits: BMI, obesity (being in the obese/overweight group), waist circumference, insulin resistance (HOMA-IR) and fasting insulin." (PMID 33048947, 2020).
Insulin resistance (continued). "In total, ten studies have assessed insulin resistance indices in women with PCOS, among which seven studies reported concentration of fasting insulin, and ten studies reported HOMA-IR and six studies evaluated QUICKI." (PMID 33424968, 2020). "Insulin resistance is an early metabolic abnormality of type 2 diabetes (T2DM), which results in hyperinsulinemia due to decreased insulin reactivity." (PMID 33134388, 2020). "The fact that sodium vanadate, an inhibitor of phosphorylation of IRS-1ser307, can recover insulin secretion indicates that high levels of T3 can inhibit insulin signal transduction in β-cells via the IRS-1/PI3-K/Akt pathway and result in insulin resistance." (PMID 32774144, 2020). "Of note, in both cohorts, indices of reduced insulin resistance such as the increase of OGIS and the suppression of fasting insulin secretion rate correlated strongly with physical activity." (PMID 32002573, 2020). "Blood parameter levels (glucose, insulin, HOMA-IR (Homeostatic Model Assessment—Insulin Resistance), HDL-cholesterol, LDL-cholesterol, triglycerides) of the examined individuals from study group." (PMID 32598403, 2020). "Homeostatic model assessment, IR = insulin resistance (HOMA-IR) was calculated by using the obtained insulin and fasting blood glucose values before neoadjuvant chemotherapy (fasting insulin × fasting glucose/405)." (PMID 32907593, 2020). "There are simple, reliable, and reproducible indices to measure insulin resistance, such as the homeostasis model assessment—insulin resistance (HOMA-IR) index, the McAuley index, and the quantitative insulin sensitivity check index (QUICKI)." (PMID 32397662, 2020). "We evaluated the effect of WSE on insulin resistance in HFD-fed mice using an oral glucose tolerance test (OGTT) and intraperitoneal insulin tolerance test (IPITT)." (PMID 32046183, 2020). "ALO treatment effectively ameliorated hyperglycemia, glucose intolerance, insulin resistance and dyslipidemia, alleviated hepatic steatosis, protected pancreatic islet function and activated GLUT4 expression in insulin target tissues of T2DM rats." (PMID 33568989, 2020). "HFD markedly increased glucose intolerance and insulin resistance, as indicated by the greater area under curve (AUC) of glucose both in the intraperitoneal glucose tolerance test (IGTT) and intraperitoneal insulin tolerance test (IITT)." (PMID 32013093, 2020). "MCT1+/− mice displayed normal insulin sensitivity, whereas MCT1+/− mice fed with a high-fat diet were resistant to diet-induced obesity, insulin resistance and glucose intolerance." (PMID 32977552, 2020). "To investigate insulin resistance development in the offspring of obese dams, we evaluated hepatic AKT phosphorylation stimulated by insulin using two protocols (in vivo and ex-vivo)." (PMID 31913329, 2020). "The data from biochemical analysis showed that polydatin significantly decreased serum concentrations of insulin, TG, IL‐1β and TNF‐α, and alleviated insulin resistance in OGTT and ITT in fructose‐fed rats." (PMID 33058500, 2020). "To further confirm effects on glucose metabolism and insulin sensitivity, we performed OGTT and ITT, suggested impaired glucose tolerance and insulin resistance (P < 0.05)." (PMID 32082261, 2020). "In the present study, AD-Con rats showed increased systemic insulin resistance, as measured by IPITT compared to normal-Con, and AD-TKK improved systemic insulin tolerance." (PMID 32326255, 2020). "Direct NOD1 activation led to insulin resistance and gut microbial derived NOD1 ligands promoted insulin trafficking in beta cells." (PMID 33178196, 2020). "Supporting the DAG model of insulin resistance, in obese subjects with non-alcoholic fatty liver disease (NAFLD), hepatic DAG content negatively correlated with insulin-induced suppression of hepatic glucose production." (PMID 32455838, 2020).
Insulin resistance (continued). "On the other hand, subjects with greater subcutaneous adipocyte size (SAS) displayed higher homeostasis model assessment of insulin resistance (HOMA-IR), blood glucose level, and plasma insulin level." (PMID 33021706, 2020). "Supplementation with RWE for 8 weeks decreased the homeostasis model assessment for insulin resistance (HOMA-IR), which indicates an increase in insulin sensitivity." (PMID 33053742, 2020). "The study revealed a considerable decrease in body weight, body fat mass, fasting blood glucose (FBG), fasting serum insulin (FSI), and Homeostasis Model of Assessment-Insulin Resistance (HOMA-IR) after eight weeks of treatment." (PMID 32148647, 2020). "In addition, in vitro cell experiments showed that flavonoids can improve insulin resistance by activating PI3K-Akt insulin signaling However, it is still unknown whether TFST has hypoglycemic activity in spontaneous diabetic animals, as well as the underlying mechanism." (PMID 33149860, 2020). "In response to postweaning high-fat diet, serum insulin level and HOMA-IR, which are used as surrogate measures of insulin resistance, were increased in offspring of dams fed a control diet." (PMID 32316103, 2020). "The ability of ER stress to activate the inflammatory c-Jun N-terminal kinase (JNK) pathway and impair insulin signaling via serine phosphorylation of IRS1 supports a potential mechanistic link between ER stress and insulin resistance in the hippocampus." (PMID 33092099, 2020). "HI abolished the acute-insulin-induced increase in GLUT4 plasma membrane levels, indicating insulin resistance, and this response was restored in the presence of RSV (HI: 100%, HI+I: 92% ± 6.0 %, RSV+HI+I: 160% ± 11% of HI, p < 0.01)." (PMID 32230718, 2020). "HFD mice exhibited elevated blood glucose and insulin levels resulting in increased values for HOMA-IR, which indicates a higher degree of insulin resistance, compared to SD mice." (PMID 32074961, 2020). "To determine whether overexpression of Nanog prevents Aβ-impaired neuronal insulin signaling, we performed western blotting to detect the level of insulin receptor substrate 1 (IRS-1) phosphorylation at Ser307, a typical marker linked to the severity of insulin resistance." (PMID 32471175, 2020). "In order to maintain normoglycemia with the development of insulin resistance (IR), a body of GDM pregnant woman secrete an increased amount of insulin, which is accompanied by less glucose utilization." (PMID 33105558, 2020). "Calculated indices of insulin resistance, HOMA-IR and Matsuda index suggested lower whole body insulin sensitivity in FDR." (PMID 33658980, 2020). "Aβ, in turn, induces insulin resistance and GSK-3β by trapping insulin receptors in the neuronal cytoplasm and promoting inhibitory serine phosphorylation of insulin pathway components, for example IRS-1." (PMID 33381011, 2020). "Plasma glucose, insulin, and glucagon and HOMA-IR levels were measured to assess the effects of AL supplementation on insulin resistance." (PMID 32796637, 2020). "In the state of insulin resistance, IRS-1 serine phosphorylation inhibits insulin signaling by decreasing tyrosine phosphorylation, and thereby inhibits downstream effectors in insulin signal transduction, such as PI3K, Akt and GSK-3β." (PMID 31952248, 2020). "Myostatin has been shown to induce insulin resistance by degrading IRS1 proteins and diminishing insulin-induced IRS1 tyrosine phosphorylation, thus interrupting insulin signaling cascade." (PMID 32831068, 2020). "Although BMI is strongly related to plasma glucose, insulin and lipid levels, sitting less and moving more seem to associate with lower plasma insulin and insulin resistance regardless of BMI, whereas overweight may have a stronger impact on glucose than either PA or SB have." (PMID 33239818, 2020). "Palmitate induced insulin resistance in C2C12 myotubes, as evidenced by a two-fold reduction in the insulin-stimulated AKT S473 phosphorylation in BPI and BPH groups." (PMID 32041341, 2020).
Insulin resistance (continued). "Beneficial modulations in insulin and HOMA-IR (an insulin resistance marker) were observed by the ICR diet." (PMID 33028352, 2020). "During OGTT, insulin secretion of NZO increased notably after the first phase, indicating insulin resistance." (PMID 32374082, 2020). "Consistently with these findings, GM3S KO mice displayed enhanced insulin signaling and were protected from HFD-induced insulin resistance." (PMID 32731387, 2020). "In addition, increased ROS production may modulate insulin signaling and inflammatory processes, thus promoting insulin resistance and inflammation, which are important features of NAFLD progression; however, the specific mechanisms underlying oxidative stress–promoted NAFLD need further study." (PMID 33371482, 2020). "Though insulin-resistance-related hyperinsulinemia and DM-related chronic inflammation promote HCC development, specific DM-associated mechanisms, including reduction of hepatic glycolysis and impairment of insulin hypersecretion, may exert anti-tumor effects in sorafenib-treated HCC." (PMID 33382703, 2020). "Insulin resistance index (HOMA-IR) and insulin secretion index (HOMA-B) were calculated to evaluate insulin resistance." (PMID 32774440, 2020). "Studies from human patients on hemodialysis with insulin resistance and patients with CKD, showed that alkalizing treatment with oral sodium bicarbonate significantly improved insulin sensitivity and secretion." (PMID 32977552, 2020). "Circadian disruption, especially constant darkness, induces insulin resistance of PCOS in rats, including increased fasting blood glucose level and increased serum insulin and leptin levels." (PMID 32334629, 2020). "Although the final body weight of HFD‐fed 20m OPN‐KO mice was similar to their age‐matched HFD‐fed WT mice, they developed a greater degree of insulin resistance as demonstrated by the insulin tolerance test (ITT), insulin levels, and HOMA‐IR." (PMID 32638492, 2020). "CSAT+® supplementation reduced blood glucose, Homeostatic Model Assessment of Insulin Resistance (HOMA-IR) and circulating levels of total cholesterol, low-density lipoprotein (LDL) cholesterol (LDL-c), insulin, and interleukin-6 (IL-6)." (PMID 32326269, 2020). "For example, the homeostatic model assessments can be used to quantify insulin resistance (HOMA-IR) based on fasting glucose and insulin levels." (PMID 32124065, 2020). "Therapeutic efficacy comparison between ProINS-Tf and INS in NOD mice with severe hyperglycemia and insulin resistance were performed in a meal challenge study." (PMID 32382087, 2020). "The homeostatic model assessment values for insulin resistance (HOMA-IR), calculated by insulin (μU/ml) × glucose (mM)/22.512, of the HYP group tended to be lower than the HFD group." (PMID 32408410, 2020). "iNOS−/− mice also displayed systemic insulin resistance as evident by ITT, PTT, and increased circulating insulin levels, HOMA-IR, decreased QUICKI, and unchanged HOMA-B." (PMID 32806494, 2020). "In order to further investigate the therapeutic effect of MNAM on insulin resistance, we examined protein expression and phosphorylation levels of IRS2, PI3K, AKT, and GSK3β, part of the hepatocyte insulin signaling pathway, by Western blot." (PMID 32280711, 2020). "Several studies have shown vitamin E tocopherols to increase insulin sensitivity by upregulating peroxisome proliferator-activated receptor (PPAR) activity, which is correlated with insulin resistance and type 2 diabetes when its activity is disrupted." (PMID 33261162, 2020). "FGF21 is also found to increase insulin sensitivity and endogenous FGF21 is believed to protect obese individuals against insulin resistance." (PMID 32590936, 2020). "The homeostasis model assessment of insulin resistance (HOMA-IR) was computed from third trimester fasting plasma glucose and insulin values." (PMID 32041106, 2020).
Insulin resistance (continued). "The insulin resistance index HOMA-IR and the insulin secretion index HOMA-β of the AGM were higher than those of the NGT (p < 0.01)." (PMID 32454945, 2020). "The Glucose-Insulin Index (product of the AUC for glucose and insulin in the OGTT), which is an indicator of insulin resistance, was significantly greater (P<0.005) for AS160-KO (4.65 ±0.87, n = 6) versus WT (1.36 ±0.15, n = 6) rats." (PMID 32053588, 2020). "Another study investigated the effect of the treatment of Brazilian propolis (100 and 300 mg/kg) for four weeks on insulin resistance in Otsuka Long-Evans Tokushima Fatty (OLETF) rats, a non-insulin-dependent type 2 diabetic model." (PMID 33383693, 2020). "During insulin stimulation (HEC), insulin sensitivity (M-value) was reduced by 41% after CAT compared with CTR, reflecting peripheral insulin resistance." (PMID 33151986, 2020). "One of the most commonly used is the homeostasis model assessment (HOMA) of insulin resistance (HOMA-IR), requiring only fasting blood glucose and insulin measurement." (PMID 33066504, 2020). "Moreover, chronic exposure to elevated levels of advanced glycosylation end-products and the direct effect exogenous insulin, determining increased serum levels of insulin in cases of insulin resistance, might be responsible for vascular injury and premature atherosclerosis." (PMID 32471222, 2020). "Correlations between glycemic parameters (fasting blood glucose, glycosylated hemoglobin, homeostasis model assessment of insulin resistance (HOMA-IR), and insulin) and BMI were also analyzed." (PMID 32498226, 2020). "Insulin resistance is a common feature of PCOS and is more often seen in obese women, suggesting that PCOS and obesity have a synergistic effect on the magnitude of insulin dysregulation." (PMID 31654312, 2020). "In a meta-analysis of RCTs, higher intakes of plant-based polyunsaturated fatty acids showed beneficial effects on insulin resistance (HOMA-IR) and fasting insulin levels compared to higher intakes of carbohydrate or saturated fatty acids." (PMID 33264277, 2020). "The Matsuda index was calculated from multiple time points of glucose and insulin after IPGTT and is a reliable indicator of overall insulin resistance." (PMID 32280711, 2020). "Mean insulin and HOMA-IR levels were suggestive of hyperinsulinemia and insulin resistance, respectively." (PMID 32668588, 2020). "The HOMA-IR (as the index of insulin resistance) and QUICKI (as a marker for insulin sensitivity), as well as HOMA-β cell function were significantly alleviated as a result of treatment of diabetic rats with leaf and fruit peel extracts." (PMID 32047529, 2020). "Accordingly, the higher is insulin, the lower is FSH, thus reflecting the importance of treating insulin resistance prior to FSH administration in oligozoospermic patients." (PMID 32681384, 2020). "Clinical investigations in both boys and girls during puberty have shown that SHBG is a strong predictor of insulin sensitivity and a decline in SHBG predicts the development of insulin resistance." (PMID 33139661, 2020). "The MAO group had worse metabolic status than the MHNW group, as indicated by higher C-peptide levels, insulin levels, glucagon levels, HOMA-IR index values, and insulin resistance rates." (PMID 32811450, 2020). "Mice fed the HFD exhibited higher body weights (~60%), fasted blood glucose levels (~70%), fasted serum insulin levels (~450%) and HOMA-IR values (~900%) compared to LFD controls, demonstrating the development of obesity and whole body insulin resistance." (PMID 32630335, 2020). "In insulin-resistant C2C12 cells, HGSD increased glucose uptake and consumption and improved insulin resistance." (PMID 32792855, 2020). "HFD-fed NOD2−/− mice also demonstrated more insulin resistance, as shown by the ITT test, and higher levels of serum insulin in comparison to WT mice on the HFD, confirming a state of hyperinsulinemia." (PMID 32774333, 2020).